RNU2-27P (RNA, U2 small nuclear 27, pseudogene)
Gene: Small nuclear RNA gene on chromosome 18 (9,518,119 to 9,518,260, reverse strand). Ensembl gene ENSG00000251994.
Homologues: Orthologues: macaque U2 (84% identical), guinea pig U2 (52% identical), guinea pig U2 (46% identical), dog U2 (45% identical), rabbit U2 (44% identical), dog U2 (43% identical), rabbit U2 (40% identical), rabbit U2 (39% identical), rabbit U2 (38% identical), rat LOC120094530 (36% identical), dog U2 (35% identical), rabbit U2 (35% identical), and 21 more. Paralogues in human: RNU2-59P (77% identical), U2 (74% identical), U2 (73% identical), RNU2-3P (73% identical), RNU2-26P (71% identical), RNU2-57P (71% identical), RNU2-6P (71% identical), RNU2-14P (70% identical), RNU2-25P (70% identical), RNU2-32P (70% identical), RNU2-48P (70% identical), RNU2-64P (70% identical), and 65 more.